ACE (angiotensin I converting enzyme)
Diseases named in the same sentence as ACE in open-access papers (continued):
Sharing a sentence is not in itself a finding about the gene and the disease.
breast carcinoma (continued). "These evaluations enable the cardio-oncology team to provide breast cancer patients with timely and optimal prevention methods utilizing various cardioprotective agents, such as beta blockers, statins, aldosterone antagonists, ACE inhibitors, dexrazoxane, etc.." (PMID 38392041, 2024). "Additionally, flavonoids can block the angiotensin-converting enzyme (ACE), which is associated with increased blood pressure; inhibit enzymes which are linked to estrogen and implicated in breast cancer; and suppress cyclooxygenase, a known source of prostaglandins." (PMID 37513277, 2023). "There was little evidence of association of genetically proxied ACE inhibition with risk of breast cancer (OR 0.98, 95% CI 0.94 to 1.02, P = 0.35), lung cancer (OR 1.01, 95% CI 0.92 to 1.10; P = 0.93), or prostate cancer (OR 1.06, 95% CI 0.99 to 1.13; P = 0.08)." (PMID 35113855, 2022). "Thus, we can conclude that the polymorphisms of ACE and AGTR1 genes could be considered as a risk factor of breast cancer, taking into consideration racial disparity." (PMID 34539580, 2021). "An insertion/deletion (I/D) polymorphism in intron 16 of ACE and a single nucleotide polymorphism (SNP) A1166C found in 3'untranslated region (UTR) of AGTR1 are reported to be implicated in various diseases; however their association with Breast Cancer (BCa) is still a topic of debate." (PMID 29460395, 2018). "High expression of ACE suggested a poorer prognosis in hematologic tumors (GSE4475, E-Tabm-346) but a better prognosis in breast cancer and colorectal cancer." (PMID 34671200, 2021). "In our investigation, we observed that ACE increased breast tissue CAT,GPx, and SOD enzymes in DMBA-induced breast cancer." (PMID 31826147, 2019). "Aside from our results, such a conclusion stems also from recent reports suggesting significant effects of an imbalance between activities of angiotensin-converting enzymes (ACE and ACE2) in the development of breast cancer." (PMID 22581182, 2012). "Our own findings using a much larger dataset are therefore important in providing reassurance that BBs, ACE inhibitors/ARBs and CCBs do not worsen survival outcomes in patients with breast cancer and support their use when necessary." (PMID 41163361, 2025). "The effect of genetic variation of ACE and AGTR1 genes on breast cancer in different ethnicity." (PMID 34539580, 2021). "AT1R upregulation in ovarian cancer and increased expression of AT1R and ACE in prostate cancer, and AGTR1 in breast cancer; localized RAS presence in gastric cancer and its correlation with tumor spread and progression; demonstrate strong associations of RAS with various cancers." (PMID 33237942, 2020). "For example, local Ang II, predominantly exists in hypoxic regions of nasopharyngeal carcinoma and breast cancer cells, where it is autocrinely produced by chymase-dependant rather than ACE dependent mechanism." (PMID 30464806, 2018). "These include Angiotensin 1-converting enzyme gene (ACE), which has been shown to have possible mitogenic and angiogenic effects in cell line and animal models of breast cancer, and heparanase (HPR), which has been proposed as a target for the development of breast cancer directed gene therapy." (PMID 23594746, 2013). "Another study demonstrates that the RAS components, angiotensinogen, renin, ACE and AT1R are expressed in hormone-receptor negative and ER+ve human breast cancer tissue, as well as in representative human breast cancer cells." (PMID 28416734, 2017).
Hyperglycemia (62 papers, 2011 to 2026). An increased concentration of glucose in the blood. "Examples of studies which have investigated medicine initiation as a proxy for an adverse medicine event include, insulin initiation as a proxy for acute hyperglycaemia associated with olanzapine initiation, and antitussive medicine initiation as a proxy for cough associated with ACE inhibitors." (PMID 24886247, 2014). "The cornerstone for the management of DKD extends beyond lowering hyperglycemia, and it includes renoprotective strategies such as the use of angiotensin receptor blockers (ARBs) and angiotensin-converting enzyme inhibitors (ACE inhibitors)." (PMID 41601953, 2026). "Recently, DN management depends on hyperglycemia control and blood pressure management using angiotensin-converting enzyme (ACE) inhibitors and angiotensin II receptor blockers (ARB)." (PMID 40531227, 2025). "This includes avoiding nephrotoxic drugs for 48 h (e.g., AT II blockers, ACE inhibitors), avoiding hyperglycemia, monitoring serum creatinine levels and urine output monitoring, and maintaining fluid balance." (PMID 40142306, 2025). "Peptides sourced from seaweed have demonstrated strong antihypertensive effects by inhibiting ACE, and displayed additional benefits such as lowering cholesterol levels, reducing hyperglycemia, and acting as antioxidants." (PMID 37432202, 2023). "In diabetic state, hyperglycemia activates ACE in the myocardium, generated a large amount of angiotensin II (Ang II), which stimulated the proliferation of myocardial fibroblasts and collagen synthesis, eventually led to myocardial interstitial fibrosis." (PMID 36699034, 2022). "Administration of angiotensin-converting enzyme (ACE) inhibitors, Angiotensin II type-I Receptor Blockers (ARBs), and thiazolidinediones (TZDs) to control hyperglycemia is related to increased expression of ACE2 receptor." (PMID 34205044, 2021). "A number of treatments, including some ACE inhibitors, perhexiline, statins, and reversal of severe hyperglycemia have been shown to ameliorate NO• resistance." (PMID 32508651, 2020). "Fermented pepper extract using water was evaluated about antioxidant activity, ACE and enzymes relevant for hyperglycemia inhibition effects." (PMID 31615144, 2019). "NaHS also inhibited hyperglycemia-induced ACE-Ang II-AT1R activation in cultured renal mesangial cells and kidneys from diabetic rats." (PMID 29066981, 2017). "Application of NaHS, an H2S donor, inhibited hyperglycemia-induced ACE-Ang II-AT1R activation in cultured renal mesangial cells and kidneys from diabetic rats." (PMID 29066981, 2017). "Administration with C66 negatively regulated hyperglycaemia-or HG-induced ACE expression and subsequent Ang II increase, which was associated with the renoprotective effects of C66 in diabetes." (PMID 24330074, 2014). "Post-hoc analysis of the HOPE trial demonstrated a 32% reduction in the incidence of development of new-onset diabetes (insulin resistance and hyperglycemia) in patients treated with the ACE inhibitor, ramapril." (PMID 22829804, 2012). "On the one hand, hyperglycemia-induced oxidative stress and inflammatory responses can interfere with the intracellular signal transduction pathway, inhibiting the transcription and translation of the ACE gene and reducing its expression level." (PMID 40282274, 2025). "Additionally, IR-induced hyperglycemia upregulates the expression of angiotensinogen, angiotensin-converting enzyme (ACE), and angiotensin II, leading to overactivation of the renin–angiotensin–aldosterone system (RAAS)." (PMID 40964523, 2025). "However, few studies demonstrate the mechanism by which hyperglycaemia up-regulates the expression of ACE gene." (PMID 24330074, 2014). "Since ACE-inhibitors including ramipril may provide renoprotection despite their inability to completely prevent renal fibrosis, we first investigated whether ramipril was able to modulate hyperglycemia-induced K63 ubiquitination." (PMID 34068941, 2021).
Hyperglycemia (continued). "Thus, this study suggests that serum ACE activity may be a more useful index for manifesting the adverse effect of hyperglycemia or Aβ accumulation on logical memory in diabetic patients." (PMID 28066203, 2016). "The study used hearts subjected to high glucose levels to mimic acute hyperglycemia and diabetic hearts isolated from four- and six-weeks diabetic rats treated at reperfusion with RAS member antagonists (ACE and AT1R)." (PMID 37259385, 2023). "Soybean peptides have an angiotensin-converting enzyme (ACE) and dipeptidyl-dipeptidases-IV inhibitory action, lowering hyperglycemia and blood pressure." (PMID 36992908, 2023). "Hyperglycemia activates local RAS by upregulating intracellular RAS components including renin, ACE, and chymase (an Ang II-generating enzyme) in mesangial cells, AT1R, AT2R, and renin in endothelial cells, and renin and AT1R in podocytes." (PMID 34289001, 2021). "The significantly higher ACE/ACE2 ratio observed in MetS correlates well with the increased systolic blood pressure and hyperglycemia in our pig model." (PMID 34611227, 2021). "Several pharmacotherapies including statins, some angiotensin-converting enzyme (ACE) inhibitors, perhexiline, and insulin (in the presence of severe hyperglycemia) ameliorate NO• resistance, while sGC activators primarily circumvent the problem." (PMID 32508651, 2020). "Interestingly, C66 administration does not affect angiotensinogen and renin expression, but significantly reduced ACE mRNA levels (P < 0.001), indicating that the reduction in Ang II level by C66 may result from its inhibition of hyperglycaemia-induced ACE overexpression." (PMID 24330074, 2014). "Empagliflozin reversed these changes in the presence of hyperglycaemia but did not affect ACE or AT1R in control cells in the absence of hyperglycaemia." (PMID 37055837, 2023). "Treatment with 2,3,5,4′-tetrahydroxystilbene-2-O-β-d-glucoside could inhibit hyperglycaemia-induced mRNA and protein expression of AGT, renin, ACE, and AT1R in mice with DN induced by streptozotocin." (PMID 36059935, 2022). "The results suggest that effective control of both hyperglycemia and blood pressure with combined treatment with SGLT2 and ACE inhibitors is an attractive therapeutic option for treatment of both type 1 and 2 diabetes that can slow the development and progression of CKD." (PMID 26169541, 2015). "Here, we further showed that C66 could affect HG/hyperglycaemia-induced renal RAS activation, including ACE expression and subsequent Ang II secretion, in a MAPK-dependent manner." (PMID 24330074, 2014). "ACE inhibitors and AT1 receptor blockers prevent hyperglycemia-induced oxidative stress by modulating angiotensin action and production; this is of particular interest because hyperglycemia is able to directly modulate cellular angiotensin generation." (PMID 23071636, 2012). "The current standard‐of‐care treatment for DKD include the use of angiotensin‐converting enzyme (ACE) inhibitors, angiotensin receptor blockers (ARBs) and potentially sodium‐glucose cotransporter‐2 (SGLT‐2) inhibitors that primarily regulate hemodynamics and hyperglycemia." (PMID 39324545, 2024). "In addition to the ACE pathway, hyperglycemia increases Ang II generation via non-ACE pathways, including chymase, kallikrein, cathepsin G, and elastase-2 responsible for Ang II formation in human tissues." (PMID 34289001, 2021). "In addition, ramipril alone did not modify the expression of α-SMA in HK2 cells grown in high glucose, suggesting that ACE inhibition alone is not sufficient to block hyperglycemia-induced epithelial to mesenchymal transition of tubular cells." (PMID 34068941, 2021). "Treatment with angiotensin-converting enzyme (ACE) inhibitors and angiotensin receptor blockers (ARBs) has proven beneficial in delaying the progression of renal damage in type 1 and type 2 diabetic patients suggesting activation of the RAS due to hyperglycemia." (PMID 21915376, 2011).
depression (61 papers, 2009 to 2025). "Although ACE has previously been associated with DM, its inclusion in our study aims to explore its potential relevance to the severity of depression." (PMID 40367215, 2025). "Thepsychotropic potential of these medications is supported by studies demonstrating agenetic association between ACE polymorphisms and depression/schizophrenia." (PMID 35895876, 2023). "In fact, in individuals with depression, the ACE I/D polymorphism is significantly associated with HPA axis hyperactivity." (PMID 36761172, 2022). "Mutations of angiotensinogen, AT1Rs, and ACE genes were detected in some patients with depression and schizophrenia." (PMID 35207180, 2022). "A clinical trial reported that ACE inhibitors reduced the likelihood of depression risk and significantly improved general well-being, work performance, and cognitive function in 625 white men with mild hypertension administered captopril for 6 months." (PMID 36761172, 2022). "Variants in ACE gene has been shown to be associated with both secretion of cortisol and depression during late-life." (PMID 35606706, 2022). "Patients with depression carrying the D/D variant of the ACE gene show considerably greater activation of the HPA axis." (PMID 36761172, 2022). "A population-based cohort study found the ACE gene (rs1799752) is associated with the incidence of major depression in older individuals in followed up for over 12 years." (PMID 36761172, 2022). "A review by Mandelli and Serretti reported evidence that supports both inheritable and environmental influences in depression and suicidal behaviour risk for the angiotensin-converting enzyme (ACE)." (PMID 36817247, 2022). "On the other hand, changes in ACE at the genetic level and the post-transcriptional level were reported to be associated with depression and glucocorticoid (Gc) secretion." (PMID 33328497, 2020). "A few studies showed that patients with major depression carrying at least one D allele of the ACE I/D polymorphisms responded better to drug treatment than those who were homozygous for the I allele." (PMID 32367400, 2020). "ACE promoter hypermethylation in patients with clinical depression (which has been associated with cardiovascular disease), on the other hand, was linked with decreased ACE mRNA levels." (PMID 31042763, 2019). "ACE polymorphisms even seem able to influence antidepressant response, cognitive function after a depression episode in the elderly, or suicide behaviour." (PMID 28760142, 2017). "Epigenetic mechanisms also appear to be important, as altered methylation of the regulatory region of the ACE gene has been associated with depression." (PMID 28760142, 2017). "A functional insertion/deletion (I/D) polymorphism of the ACE gene was associated with risk for being a smoker among individuals with depression and with smoking severity in studies comprising patients with depression and healthy controls." (PMID 28127518, 2017). "The angiotensin converting enzyme (ACE) has been repeatedly discussed as susceptibility factor for major depression (MD) and the bi-directional relation between MD and cardiovascular disorders (CVD)." (PMID 22808171, 2012). "The ACE genotype has been shown to be associated with depression in several studies, including variants of the ACE gene linked to cortisol secretion and late life depression." (PMID 40367215, 2025). "Furthermore, polymorphism and levels of ACE are increased in the Iranian population and increase the risk of depression." (PMID 37953501, 2024). "Moreover, abnormalities in the DNA methylation pattern in ACE promoter has been identified as a causal factor for development of major depression." (PMID 35606706, 2022). "In addition, the I/D polymorphism of the ACE gene is associated with both late-life depression and cortisol secretion." (PMID 36761172, 2022).
depression (continued). "Indeed, increased plasma ACE and genotypes that promote this imbalance are associated with higher rates of depression, bipolar disorder, and psychotic symptoms, all of which can increase suicidal ideation." (PMID 34648616, 2022). "In addition, a study based on the Iranian population showed that high serum ACE activity is associated with the pathogenesis of depression." (PMID 36761172, 2022). "The D allele may be associated with the severity of depression in DD genotypes carriers of ACE I/D polymorphism." (PMID 36761172, 2022). "Additionally, we found reduced depressive outcomes when excluding individuals who had also been treated with β blockers and ACE inhibitors, other cardiovascular medications linked to depression." (PMID 33069320, 2020). "However, other single nucleotide polymorphisms have been associated with depression, including the GG genotype of ACE A2350G, which also correlated with higher ACE serum activity." (PMID 28760142, 2017). "However, the results are in disagreement with previous findings from a German population study reporting a positive association of ACE‐DD homozygosity, nicotine dependence risk, and number of cigarettes smoked daily among patients with depression." (PMID 28127518, 2017). "For instance, a longitudinal study focusing on neuropsychiatric disorders in an elderly community found that several single-nucleotide polymorphisms (SNPs) of angiotensin-converting enzyme (ACE) were significantly associated with the risk of late-life depression." (PMID 27199779, 2016). "Zill P and his colleagues analyzed the DNA methylation pattern of ACE gene in peripheral leukocytes and found that aberration of DNA methylation at ACE promoter may be an underlying cause of major depression." (PMID 26501962, 2015). "Besides its crucial role in cardiovascular homeostasis, the ACE gene confers also susceptibility for depression, as demonstrated in several genetic and expression studies." (PMID 22808171, 2012). "Although several questions remain to be resolved regarding the precise functional consequences of the identified ACE promoter DNA methylation, our data are consistent with the hypothesis that DNA methylation aberrations may be an underlying cause of depressive disorders." (PMID 22808171, 2012). "The potential roles played by Humanin, MOTS-c, p66shc, and the ACE genotype have remained largely unexplored, representing a significant gap in understanding depression and disease progression." (PMID 40367215, 2025). "In Model 2, biomarkers ranked highest on the order of p66shc, MOTS-c, and humanin while ACE ranks least showing that it is the least important variable in predicting the severity of depression in this particular Model." (PMID 40367215, 2025). "A case–control study that involved 191 patients with depression and 104 healthy controls showed that plasma ACE activity was higher in patients with depression as compared to the controls." (PMID 37953501, 2024). "Initial evidence came from studies conducted in the 1980s with hypertensive patients with depression that revealed positive effects of the ACE inhibitor captopril on both blood pressure control and depressive symptoms." (PMID 36173067, 2024). "ACE-DD homozygous females manifested higher decreases in PANSS depression factor compared to ACE-II homozygous and ACE-ID heterozygous females." (PMID 36293037, 2022). "Remarkably, ACE has been identified as the target gene for both atherothrombotic complications and management of depression." (PMID 35911513, 2022). "On the other hand, ACE-DD homozygous females exhibited greater decreases in PANSS depression factor compared to ACE-II homozygous and ACE-ID heterozygous females: −8.4 ± 2.8 vs. −6.6 ± 2.8, z = −2.53, p = 0.010, Cohen’s d = 0.64." (PMID 36293037, 2022). "Acute treatment with the ACE-inhibitor captopril appears to improve depression in an open-label trial and of lisinopril in a case series." (PMID 33362613, 2020).